ANKRD50 (ankyrin repeat domain 50)
Description:
Involved in the endosome-to-plasma membrane trafficking and recycling of SNX27-retromer-dependent cargo proteins, such as GLUT1.
Synonyms: KIAA1223
Tractability: PROTAC: ubiquitination databases record sites on it; its protein half-life has been measured.
Gene: Protein-coding gene on chromosome 4 (124,664,048 to 124,712,732, reverse strand). Ensembl gene ENSG00000151458.
Subcellular location: Endosome
Subcellular location (Human Protein Atlas): Cytosol; Nucleoplasm
Gene Ontology:
Molecular function: protein binding
Biological process: endocytic recycling
Cellular component: endosome
Genetic constraint (gnomAD): Loss-of-function variants: 39 observed, 116.06 expected, observed/expected ratio (o/e) 0.34, 90% interval 0.26 to 0.44. The upper end of that interval is the gene's LOEUF score, 0.44, which puts it in group 1 of 6, group 1 being the genes least tolerant of losing a copy. Missense variants: 1,485 observed, 1,787.9 expected, observed/expected ratio (o/e) 0.83, 90% interval 0.8 to 0.87. Synonymous variants: 612 observed, 656.01 expected, observed/expected ratio (o/e) 0.93, 90% interval 0.87 to 1.
Homologues: Orthologues: chimpanzee ANKRD50 (99% identical), macaque ANKRD50 (99% identical), dog ANKRD50 (98% identical), guinea pig ANKRD50 (98% identical), rabbit ANKRD50 (97% identical), rat Ankrd50 (95% identical), tropical clawed frog ankrd50 (86% identical), pig ANKRD50 (86% identical), zebrafish ANKRD50 (66% identical), Drosophila melanogaster CG10011 (38% identical), mouse Ankrd50 (30% identical), Caenorhabditis elegans T28D6.4 (21% identical), and 1 more.
Diseases named in the same sentence as ANKRD50 in open-access papers:
ANKRD50 is named in the same sentence as 3 diseases in open-access papers, as found by Europe PMC text mining. Sharing a sentence is not in itself a finding about the gene and the disease. The quoted sentences say what the papers report.
viral infection (1 paper, 2018). "This is the first reported association of ANKRD50 with viral infection." (PMID 30177951, 2018).
ANKRD50 also shares sentences with these, for which no sentence is quoted: asthma (1 paper); dental caries (1).